APLN (apelin)
Diseases named in the same sentence as APLN in open-access papers (continued):
Sharing a sentence is not in itself a finding about the gene and the disease.
COVID-19 (11 papers, 2020 to 2026). A disease caused by infection with severe acute respiratory syndrome coronavirus 2. "However, much has been discussed on how potential therapies involving apelin could be associated with better COVID-19 prognosis and cure expectancy." (PMID 37408184, 2023). "Although these studies may point at a diagnostic value to correlate serum apelin levels with infection and disease, the relevant cohorts consisted of 69 and 78 COVID-19 patients, respectively, and future research with larger cohorts will be needed to substantiate these findings." (PMID 37238973, 2023). "In COVID-19 patients, Apelin-13 correlated positively with glucose (r = 0.320, p = 0.032) and negatively with sodium (r = -0.323, p = 0.030)." (PMID 42322090, 2026). "For apelin, a clear difference was observed between healthy individuals, who had the highest levels, and patients with mild and severe COVID-19, who showed significantly lower values." (PMID 40003732, 2025). "Adipokines, such as apelin and visfatin, are less well-studied, and their potential as disease markers for COVID-19 is still to be clarified." (PMID 37238973, 2023). "Several studies provided insights on chemerin, adiponectin, leptin, resistin, and galectin-3 levels in SARS-CoV-2-infected patients, while limited information is yet available on the adipokines apelin and visfatin in COVID-19." (PMID 37238973, 2023). "Serum apelin has also been proposed as a biochemical factor predicting mortality in severe COVID-19 patients." (PMID 37686837, 2023). "Considering that SARS-CoV-2 reduces the amount and/or activity of ACE2 by binding to it, it is predictable that the level of apelin is reduced in COVID-19 patients." (PMID 36352477, 2022). "This study's findings showed that the serum apelin content was significantly lower in control and diabetic people with COVID-19, and the amount of its reduction levels were positively associated with the hospital duration." (PMID 36352477, 2022). "The results of the present study also revealed that NO levels were lower in COVID-19 patients, as were apelin levels." (PMID 36352477, 2022). "The findings of this study showed that the apelin and nitric oxide content was lower than normal in patients with COVID-19 on admission." (PMID 36352477, 2022). "These single-cell gene expression clusters in zebrafish are consistent with Apelin signaling in COVID-19 comorbidities in human because they act in cardiovascular development." (PMID 33757938, 2021). "Taken together, these data suggest that COVID-19-associated metabolic abnormalities are at least partially dependent on the transcription factor REST and its downstream genes, which include MPO, apelin, and myostatin." (PMID 34916489, 2021). "The conservation of RAAS/apelin components makes zebrafish an appropriate model to investigate their roles in the mechanisms of COVID-19." (PMID 33757938, 2021). "In addition, KEGG analysis showed that the genes were involved in Coronavirus disease-COVID-19, viral carcinogenesis, ribosome, apoptosis, Apelin signaling pathway, PPAR signaling pathway, and other signal transduction pathways." (PMID 38035073, 2023). "Serum apelin levels were lower in COVID-19 patients compared to healthy controls." (PMID 37238973, 2023). "The lower serum apelin levels found in COV patients in this study can be a result of its degradation by ACE2 as circulatory ACE2 has been shown to be increased in patients with COVID-19." (PMID 36352477, 2022). "The finding that the amount of apelin decreases with increase in age may be consistent with the higher rate of complications and severity of COVID-19 in older patients (because of the reduction in protective effects of apelin)." (PMID 36352477, 2022). "Considering that MPO, apelin, and myostatin showed consistent alteration patterns upon COVID-19, which is in line with their previously identified regulatory roles, we next explored the potential association between MPO, apelin, and myostatin and metabolic parameters." (PMID 34916489, 2021).
COVID-19 (continued). "Together, these data suggest that apelin or its receptor agonists could be of major interest in developing a potential treatment for COVID-19 through ACE and Ang-II suppression, as well as down-regulation of angiotensin receptor 1 (AT1R) and up-regulation of ACE2." (PMID 37686837, 2023). "This study aimed to compare the serum levels of apelin and nitric oxide in hospitalized COVID-19 patients and non-COVID-19 subjects with and without the mentioned risk factors." (PMID 36352477, 2022). "The functional significance of apelin down-regulation has not been fully elucidated, but it has been suggested that apelin may ameliorate Ang-II-mediated inflammation, thrombosis and vasoconstriction in COVID-19." (PMID 37686837, 2023). "Serum apelin levels in COVID-19 patients were not dependent on sex, smoking status, and opium use." (PMID 36352477, 2022).
lung adenocarcinoma (11 papers, 2018 to 2025). A carcinoma that arises from the lung and is characterized by the presence of malignant glandular epithelial cells. "More recently, another study indicated that miRNA inhibits lung adenocarcinoma cell proliferation and invasion though targeting APLN and provides novel insight into the mechanism underlying the development of lung adenocarcinoma." (PMID 36614283, 2023). "To clarify the molecular mechanism underlying apelin exerting its effects on lung adenocarcinoma cells, we identified a putative miR‐195 binding site located in the 3′‐UTR of the apelin mRNA using Pictar, TargetScan, and miRanda online tools." (PMID 31070305, 2019). "Our results show that miR‐195 functions as a tumor suppressor in lung adenocarcinoma and implicate miR‐195‐apelin as a potential diagnostic and therapeutic target for human lung adenocarcinoma." (PMID 31070305, 2019). "Our data constitute evidence that miR‐195 inhibits lung adenocarcinoma cell proliferation and invasion though targeting apelin and provides novel insight into the mechanism underlying the development of lung adenocarcinoma." (PMID 31070305, 2019). "Both high levels of apelin and low levels of miR‐195 in lung adenocarcinoma tissues are associated with poor survival." (PMID 31070305, 2019). "Furthermore, survival analysis showed that apelin expression in the 36 tumor samples was observably associated with the OS of lung adenocarcinoma patients." (PMID 31070305, 2019). "On the other hand, in lung adenocarcinoma, apelin-13 (the 13 amino acid form) induces proliferation through the activation of ERK1/2, facilitating the expression of cyclin D1 and the induction of autophagy." (PMID 36291097, 2022). "In lung adenocarcinoma cell lines, it was shown that apelin-13 promotes proliferation through the expression of cyclin D1 mediated by the phosphorylation of ERK1/2." (PMID 36291097, 2022). "Our study demonstrated that the levels of apelin mRNA and protein are both negatively regulated by miR‐195 in lung adenocarcinoma cells and the apelin expression level is inversely correlated with miR‐195 expression." (PMID 31070305, 2019). "In conclusion, this study identified miR‐195 as a tumor‐suppressive factor in human lung adenocarcinoma by directly targeting apelin." (PMID 31070305, 2019). "We confirmed that miR‐195 exerts a tumor suppressor role by targeting apelin mRNA in lung adenocarcinoma cells." (PMID 31070305, 2019). "The expression level of miR‐195 was inversely correlated with the expression level of apelin mRNA in the lung adenocarcinoma tissues." (PMID 31070305, 2019). "In the present analysis of clinical human lung adenocarcinoma tissues, the apelin mRNA level was negatively correlated with the expression level of miR‐195." (PMID 31070305, 2019). "Further analysis revealed that apelin is one of the functional target genes of miR‐195, and the overexpression of apelin efficiently inhibits the promotion of cell proliferation and invasion mediated by miR‐195 mimics in lung adenocarcinoma cells." (PMID 31070305, 2019). "In the present study, we detected the expression of apelin in 36 paired human lung adenocarcinoma and adjacent healthy lung tissues using immunohistochemistry staining." (PMID 31070305, 2019). "The effects of miR‐195 and apelin on the proliferation and cell cycle of lung adenocarcinoma cells were assessed by methyl thiazolyl tetrazolium and colony formation assays, and flow cytometry." (PMID 31070305, 2019). "Meanwhile, using qRT‐PCR and Western blotting assay, we found that both the expression levels of apelin mRNA and protein were significantly increased in the lung adenocarcinoma tissues compared to the adjacent healthy lung tissues." (PMID 31070305, 2019). "We aimed to identify the effects of miR‐195 on inhibiting apelin and clarify the regulating mechanism of miR‐195‐apelin in lung adenocarcinoma cells." (PMID 31070305, 2019).
lung adenocarcinoma (continued). "The expression level of apelin and miR‐195 showed an inverse correlation in lung adenocarcinoma tissues and cell lines." (PMID 31070305, 2019). "Further investigation is required to elucidate the role of molecules that are downstream of apelin in regulating cell proliferation, migration, and invasion of lung adenocarcinoma." (PMID 31070305, 2019). "Taken together, these results confirm that apelin is a functional target of miR‐195 in lung adenocarcinoma cells and validates the function of miR‐195‐apelin interaction in the progression of lung adenocarcinoma." (PMID 31070305, 2019). "Collectively, high miR‐195 and low apelin work synergistically, suppressing tumor growth and improving the survival outcome of lung adenocarcinoma patients." (PMID 31070305, 2019). "Apelin also contributed to lung adenocarcinoma resistance to chemotherapy-induced inhibition of cell metastasis." (PMID 30127323, 2018). "Similar results were obtained when examining apelin-13 influence on lung adenocarcinoma A549 migration abilities." (PMID 30127323, 2018). "In vitro studies have demonstrated, that apelin-13 promotes the proliferation of human lung adenocarcinoma cells through an upregulation of cyclin D1 level and thus accelerating the conversion of G0/G1 to S phase in the cell cycle." (PMID 29875677, 2018). "Apelin could also increase cell migration in lung adenocarcinoma, GC and oral squamous cell carcinoma." (PMID 33912466, 2021). "In addition, luciferase reporter assay confirmed that apelin is a direct target gene of miR‐195 in lung adenocarcinoma cells." (PMID 31070305, 2019). "In addition, functional research also showed that apelin was positively correlated with cell proliferation, migration, and invasion of lung adenocarcinoma." (PMID 31070305, 2019). "In the present study, we found that apelin exhibited a higher level of expression, whereas miR‐195 was significantly downregulated in human lung adenocarcinoma samples and cell lines, in which apelin mRNA expression was inversely correlated with the miR‐195 level." (PMID 31070305, 2019). "Additionally, apelin-13 promotes lung adenocarcinoma cell migration via the PAK1-cofilin pathway." (PMID 36291097, 2022). "Furthermore, a high expression of autophagy-related genes in lung adenocarcinoma was identified, and it was shown that apelin-induced autophagy is required for lung adenocarcinoma cell migration, where cofilin phosphorylation was necessary for autophagy induction mediated by apelin." (PMID 36291097, 2022). "Interestingly, a recent study revealed that miR-195 could directly target apelin, thus inhibiting lung adenocarcinoma cell proliferation and invasion." (PMID 33912466, 2021). "Cell migration assays revealed, that apelin-13 and APJ were responsible for increased migration abilities of human lung adenocarcinoma cells via the PAK1-cofilin signaling pathway." (PMID 29875677, 2018).
prostate carcinoma (11 papers, 2018 to 2025). A carcinoma that arises from epithelial cells of the prostate gland. "Our data indicated higher levels of apelin expression in PC3 cells than in DU145 and LNCaP cells, implying that apelin is associated with migratory capacity in prostate cancer lines." (PMID 36291151, 2022). "Consistently, analyses of the Oncomine database and GEPIA tool, as well as IHC data from the tissue array, confirmed significantly upregulated apelin expression in prostate cancer samples and higher levels of apelin were negatively associated with survival." (PMID 36291151, 2022). "In conclusion, we reveal that apelin increases integrin αvβ3 synthesis and promotes prostate cancer metastasis by activating STAT3 and inhibiting miR-8070 via the MAPK pathway." (PMID 40612675, 2025). "Further development of therapies targeting the apelin/integrin axis will benefit prostate cancer patients undergoing treatment." (PMID 40612675, 2025). "Inhibiting apelin reduces prostate metastasis in vivo, indicating that the apelin/integrin αvβ3 axis is a promising target for treating prostate cancer metastasis." (PMID 40612675, 2025). "Activation of STAT3 and inhibition of miR-8070 through the MAPK pathway are involved in apelin-induced prostate cancer migration." (PMID 40612675, 2025). "Ex vivo IVIS analysis revealed that apelin blockade inhibited prostate cancer metastasis to the liver and bone by 50% and 75%, respectively." (PMID 40612675, 2025). "Apelin enhances wound healing and cell migration in prostate cancer by promoting integrin αvβ3 production." (PMID 40612675, 2025). "Cell culture experiments demonstrated that apelin promotes integrin αvβ3-dependent prostate cancer migration by activating STAT3 and inhibiting miR-8070 via the MAPK pathway." (PMID 40612675, 2025). "In this study, elevated apelin and integrin αvβ3 expression levels were detected in prostate cancer samples compared to those in normal individuals." (PMID 40612675, 2025). "Next, we used a wound healing migration assay to examine the migratory effects of apelin in prostate cancer cells." (PMID 40612675, 2025). "Here, we found that apelin and integrin αvβ3 expression levels were elevated in prostate cancer samples compared to those in normal individuals." (PMID 40612675, 2025). "Here, we found that apelin and integrin αvβ3 are upregulated in prostate cancer patients compared to healthy individuals." (PMID 40612675, 2025). "Subsequent studies showed that apelin administration decreased miR-8070 expression and that the introduction of a miR-8070 mimic into prostate cancer cells reversed apelin-induced integrin αv and β3 production, thereby reducing cell motility." (PMID 40612675, 2025). "Other adipokines that have been shown to play a role in prostate cancer progression include apelin and resistin." (PMID 39596205, 2024). "Through the APJ axis, apelin downregulates tissue inhibitors of matrix metalloproteinases (TIMP2) expression to increase prostate cancer progression and metastasis." (PMID 39596205, 2024). "In prostate cancer, upregulation of APLN is more frequently occurred in tumor tissues with advanced pathologic stage, metastasis, prostate-specific antigen failure, and shorter biochemical recurrence-free survival." (PMID 36614283, 2023). "Our data showed that the PI3K and Akt inhibitor or siRNA antagonized apelin-mediated TIMP2-dependent prostate cancer motility." (PMID 36291151, 2022). "We observed that apelin promoted prostate cancer cell migration and invasion that was antagonized when the cells were transfected with TIMP2 overexpression." (PMID 36291151, 2022). "Our results indicate that high levels of apelin are positively related with increasing tumor stage, poor survival and metastasis in prostate cancer." (PMID 36291151, 2022). "Our investigation found higher levels of apelin expression in human prostate cancer tissue than in normal healthy samples." (PMID 36291151, 2022).
prostate carcinoma (continued). "Upregulation of apelin expression predicts a poor prognosis with lower survival in patients with prostate cancer." (PMID 36291151, 2022). "Treatment of prostate cancer cells with the c-Src inhibitor (PP2) or siRNA antagonized apelin-regulated effects on TIMP2 expression, cell migration and invasion." (PMID 36291151, 2022). "Analysis of the database revealed a positive correlation between apelin level with the progression and metastasis of prostate cancer patients." (PMID 36291151, 2022). "Overexpression in LNCaP cells (lowest expressed apelin) or knockdown of apelin in PC3 cells (highest expressed apelin) promoted and reduced prostate cancer cell motility, respectively, suggesting that apelin facilitates prostate cancer migration and invasion." (PMID 36291151, 2022). "Apelin also appeared to promote the migration and invasion of prostate cancer cells by inhibiting TIMP2 production." (PMID 36291151, 2022). "In this study, apelin overexpression clearly enhanced the motility of androgen-dependent prostate cancer cells (the LNCaP cell line)." (PMID 36291151, 2022). "Elevating miR-106a-5p expression via the c-Src/PI3K/Akt signaling cascades was mediated in apelin-induced promotion of prostate cancer motility." (PMID 36291151, 2022). "The knockdown of APLN in prostate cancer cells resulted in the abolished effect of miR-224, including inhibition of migration and invasion." (PMID 29875677, 2018). "Downregulation of miR-244 and upregulation of APLN correlated with aggressiveness of tumor progression in patients with prostate cancer." (PMID 29875677, 2018). "Importantly, our in vivo study indicated that inhibiting apelin reduces integrin αvβ3 expression and prostate cancer metastasis." (PMID 40612675, 2025). "Importantly, the in vivo study confirmed that inhibiting apelin reduces integrin expression and prostate cancer metastasis." (PMID 40612675, 2025). "We previously demonstrated that apelin enhances prostate cancer motility 19; however, the effects of apelin on integrin expression and distant metastasis of prostate cancer remain unclear." (PMID 40612675, 2025). "Apelin stimulation enhances integrin αvβ3-dependent prostate cancer migration." (PMID 40612675, 2025). "Apelin has been found to be important for the development of many types of cancer 27, 28, however it is yet unknown how apelin affects prostate cancer metastases." (PMID 40612675, 2025). "Moreover, apelin blockade inhibited the occurrence of distant metastases and reduced the expression of apelin and integrin αvβ3 in the bone, liver, and lung, indicating that the apelin/integrin axis plays a crucial role in prostate cancer metastasis." (PMID 40612675, 2025). "A previous study has shown that targeting APLN by miRNA can inhibit the invasion and migration of prostate cancer cells, which may synergistically predict biochemical recurrence-free survival in patients." (PMID 36614283, 2023). "In addition, apelin stimulation increases miR-106a-5p expression, while treatment of prostate cancer cells with the miR-106a-5p inhibitor reversed apelin-induced inhibition of TIMP2 synthesis and promotion of cell migration and invasion." (PMID 36291151, 2022). "This study reports high levels of apelin expression in human metastatic prostate cancer samples." (PMID 36291151, 2022). "Thus, apelin induces TIMP2-dependent prostate cancer motility by increasing miR-106a-5p expression via the c-Src/PI3K/Akt pathway." (PMID 36291151, 2022). "Next, we addressed whether apelin blockade helps to prevent prostate cancer metastasis in tumor xenograft mouse models." (PMID 36291151, 2022). "Treatment with apelin-13 resulted in increased proliferation of prostate cancer cell lines." (PMID 29875677, 2018). "However, the mechanisms by which apelin regulates integrin production and metastasis in prostate cancer remain unclear." (PMID 40612675, 2025). "Therefore, integrin αvβ3 is a critical mediator of apelin-regulated prostate cancer metastasis." (PMID 40612675, 2025).